RNU6-492P (RNA, U6 small nuclear 492, pseudogene)
Gene: Small nuclear RNA gene on chromosome 9 (107,475,036 to 107,475,139, reverse strand). Ensembl gene ENSG00000199905.
Homologues: Orthologues: chimpanzee U6 (97% identical), macaque U6 (93% identical), rat U6 (92% identical), rat U6 (91% identical), mouse Gm22251 (89% identical). Paralogues in human: RNU6-25P (93% identical), RNU6-29P (93% identical), RNU6-1 (92% identical), RNU6-15P (92% identical), RNU6-2 (92% identical), RNU6-27P (92% identical), RNU6-3P (92% identical), RNU6-48P (92% identical), RNU6-4P (92% identical), RNU6-5P (92% identical), RNU6-656P (92% identical), RNU6-6P (92% identical), and 1287 more.